CCL8 (C-C motif chemokine ligand 8)
Diseases named in the same sentence as CCL8 in open-access papers (continued):
Sharing a sentence is not in itself a finding about the gene and the disease.
lung carcinoma (6 papers, 2012 to 2025). "Specifically, the plasma CCL8 levels in lung cancer patients were much higher than the levels observed in either pulmonary tuberculosis patients or tuberculous pleurisy (TP) patients." (PMID 23028695, 2012). "The abundance of bacterial populations in the stool of lung cancer patients significantly increased the levels of IL-20, IL-24, CCL-8, and TGF-α in LUAD and LUSC patients, indicating the role of these proteins in bridging the association between gut ecology and lung cancer." (PMID 41376623, 2025). "CCL1, CCL21, IP-10, CCL8 and CXCL9 levels were much higher in pleural effusions from patients with TP compared with lung cancer patients." (PMID 23028695, 2012). "Based on these results, we may surmise that CCL11 and IP-10 are specifically increased in plasma from pulmonary tuberculosis and tuberculous pleurisy patients, while CCL8 and CCL2 are specifically decreased when compared with lung cancer controls." (PMID 23028695, 2012).
prostate carcinoma (6 papers, 2017 to 2025). A carcinoma that arises from epithelial cells of the prostate gland. "Beyond the direct effect of KPNA4 suppression on prostate cancer cell growth, KPNA4 knockdown reduced M2 tumor-associated macrophage (TAM) infiltration into tumors in vivo by reducing chemokine (C-C motif) ligand 2 (CCL2) and chemokine (C-C motif) ligand 8 (CCL8) expression in prostate tumor cells." (PMID 29050362, 2017). "CCL5 belongs to the family of C-C chemokines as do CCL7, CCL8, and CCL21, which were also upregulated in prostate cancer lung metastases." (PMID 39146303, 2024).
idiopathic pulmonary fibrosis (5 papers, 2017 to 2024). Idiopathic pulmonary fibrosis (IPF) is a nonneoplastic pulmonary disease that is characterized by the formation of scar tissue within the lungs in the absence of any known cause. "As CCL8 binds to CCR1 and CCR2, its effects involve the accumulation of CCR1+ inflammatory cells and CCR2+ macrophages and fibrocytes/fibroblasts, which contribute to collagen deposition, indicating a significant role in pulmonary fibrosis." (PMID 39768150, 2024). "Although other chemokine-receptor pairs, such as CCL1, CCL8, and CCR8, garnered our attention, these findings suggest the intriguing possibility that the CXCR6-CXCL16 axis may play a role in specific immune cell recruitment and contribute to the pathogenesis of pulmonary fibrosis." (PMID 38789926, 2024).
influenza (5 papers, 2021 to 2025). An acute viral infection of the respiratory tract, occurring in isolated cases, in epidemics, or in pandemics; it is caused by serologically different strains of viruses (influenzaviruses) designated A, B, and C, has a 3-day incubation period, and usually lasts for 3 to 10 days. "We identified a range of potential biomarkers, including genes such as Ccl8, Pdcd1, Gzmk, and metabolites like kynurenine, adipoyl-carnitine, L-glutamine, which can be used for monitoring influenza risk." (PMID 40475788, 2025). "Firstly, the identified biomarkers (e.g., Ccl8, Pdcd1, kynurenine, L-glutamine) and the influenza risk scoring system remain unvalidated experimentally." (PMID 40475788, 2025). "CCL8 has also been observed to be transcriptionally increased in bronchoalveolar lavage from calves experimentally challenged with a novel viral member of the BRDC, influenza D20." (PMID 33931718, 2021).
hepatocellular carcinoma (4 papers, 2020 to 2023). A malignant tumor that arises from hepatocytes. "CCL8 released by tumor-associated monocytes and macrophages induces epithelial-mesenchymal transition and migration of hepatoma cells." (PMID 35362480, 2022). "Compared with control treatment, treatment with CCL8 triggered the migration of HepG2 hepatoma cells, substantially increased their levels of vimentin and SNAI1 expression, and downregulated their levels of E-cadherin expression." (PMID 35362480, 2022). "In hepatocellular carcinoma, lung adenocarcinoma, and uveal melanoma hypoxia does not change the expression of CCL8/MCP-2." (PMID 32781743, 2020).
lupus (4 papers, 2017 to 2025). "We found that elevated systemic IFN-γ levels induce the expression of CCL8 in neurons and the activation of microglia, which contribute to synapse loss and depression-like behavior in individuals with lupus by increasing synaptic engulfment." (PMID 40048256, 2025). "The CC-motif chemokine receptor type 5 (Ccr5), which interacts with CC-motif chemokine ligand 8 (Ccl8), was highly expressed in the lupus brain and suppressed by MSCT, as revealed by the RNA-seq data and confirmed by PCR." (PMID 40048256, 2025). "In vivo, lupus mice in which JAK/STAT1 or CCL8 signaling was inhibited were largely protected from depression and synapse loss." (PMID 40048256, 2025). "Transplanted hUCMSCs targeted Th1 cell–derived IFN-γ to inhibit neuronal JAK/STAT1 signaling and downstream CCL8 expression, reducing phagocytic microglia apposition to alleviate synaptic engulfment and neurological dysfunction in young (8-week-old) lupus mice." (PMID 40048256, 2025). "Additionally, MSCT reduced the number of Ccl8+ neurons in the brains of lupus mice." (PMID 40048256, 2025). "We found that in the brains of lupus mice, IFN-γ–regulated genes are highly expressed, IFN-γ induces neurons to secrete CCL8 via JAK/STAT1 signaling, and microglia are activated and show increased phagocytosis following entry of IFN-γ into the brain." (PMID 40048256, 2025). "Furthermore, the CCL8 concentration in the CSF was positively correlated with the System Lupus Erythematosus Disease Activity Index (SLEDAI) score in patients with SLE." (PMID 40048256, 2025). "Overall, these data demonstrate that MSCs ameliorate lupus symptoms in MRL.Faslpr mice by inhibiting the expression of inflammatory cytokines and chemokines in the kidney, with the exception of CCL8." (PMID 37567910, 2023). "We found that expression of CCL2, CCL3, CCL4, CCL5, CCL8, CCL19, and CXCL10 increased 1.6–5.6-fold in the kidney of lupus-prone MRL.Faslpr mice with advancing age from 9 to 16 weeks." (PMID 37567910, 2023). "We also found that expression of CCL2, CCL3, CCL4, CCL5, CCL8, CCL19, and CXCL10 increased 1.6–5.6-fold in the kidney of lupus-prone MRL.Faslpr mice with advancing age from 9 to 16 weeks." (PMID 37567910, 2023). "Because neurons in the healthy brain express low levels of CCL8 and microglia are not highly active, we wondered which factors in the brain are involved in the pathology of lupus-related depression." (PMID 40048256, 2025). "Thus, we speculated that in lupus, IFN-γ–induced neuronal expression of CCL8 represents a key step in communication between systemic immunity and microglia." (PMID 40048256, 2025). "Systemic delivery of exogenous IFN-γ blunted MSCT-mediated alleviation of synaptic loss and depressive behavior in lupus mice, suggesting that the IFN-γ/CCL8 axis may be an effective therapeutic target and that MSCT is a potential therapy for lupus-related depression." (PMID 40048256, 2025).
osteosarcoma (4 papers, 2021 to 2025). A usually aggressive malignant bone-forming mesenchymal neoplasm, predominantly affecting adolescents and young adults. "In osteosarcoma and melanoma, high CCL8 expression has been a good prognosticator and correlated with tumor infiltration with CD8+ T cells and M1 macrophages, while in animal models, MCP-2/CCL8 negatively affected the proliferation of melanoma cells and reduced the number of liver metastases." (PMID 34884259, 2021). "In osteosarcoma, CD16+ monocytes/macrophages secrete chemokines CCL2, CCL3, and CCL8 to enhance tumor infiltration by immune cells." (PMID 41155410, 2025). "CCL8, also known as monocyte chemoattractant protein-2 (MCP-2), was first identified in human osteosarcoma cells and functions in a wide variety of inflammatory cells as a chemotactic factor by binding chemokine receptors including CCR2." (PMID 35203308, 2022). "CCL8, also known as MCP-2, is another chemotactic cytokine found in the supernatant of human osteosarcoma cells (MG-63)." (PMID 35281057, 2022).
ovarian carcinoma (4 papers, 2017 to 2025). A malignant neoplasm originating from the surface ovarian epithelium. "However, CCL8 in addition to CCL4/5 has been reported to induce the homing of CCR1/5 + intraepithelial CD8 T cells in ovarian cancer, thereby favouring improved response." (PMID 40280979, 2025). "Moreover, we analyzed the Cancer Genome Atlas Ovarian Cancer (TCGA-OV) database, and found CD68+YAP1low groups exhibited dramatically increased M2-like TAMs markers expression, such as MMP9, CCL8, SPP1 and CCL17, when compared to CD68+ YAP1high." (PMID 39198883, 2024).
Pleural effusion (4 papers, 2005 to 2023). The presence of an excessive amount of fluid in the pleural cavity. "Protein secretion of CCL8 was previously shown to increase upon M. tb infection in various macrophage models and in pleural effusions of TB patients." (PMID 37000865, 2023).
psoriasis (4 papers, 2015 to 2023). An autoimmune condition characterized by red, well-delineated plaques with silvery scales that are usually on the extensor surfaces and scalp. "A further investigation of the effect of compounds 1 on psoriasis showed a dramatic decrease in the levels of chemokines, CCL8 and CCL20 in the TNF-α/IL-17/IFN-γ-induced HaCaT psoriasis model." (PMID 36015080, 2022). "Immune-related genes (e.g. CCL8, LCP2, CD1E) and IL-36G, which was recently associated with psoriasis pathogenesis, were increased in AD LS skin." (PMID 26459294, 2015). "Fibroblasts produced a number of chemokines (CCL13, CCL19, CCL2, CCL8, CXCL1, CXCL12, CXCL2, CXCL3) that linked to receptors expressed by myeloid cells and T cells, suggesting an important role for fibroblasts in recruiting immune cells in psoriasis." (PMID 37308489, 2023).
breast tumors (3 papers, 2020 to 2025). "More recently, breast tumor cells induced CCL8 expression in infiltrating TAMs, which in turn induced Siglec1 and enhanced monocyte recruitment and tumor cell motility." (PMID 33072601, 2020). "In human prostate and breast tumors, the CH25H gene shows a very high correlation of coexpression with the CCL2 and CCL8 genes, as is the case in the dormant‐met group." (PMID 41159143, 2025).
colon cancer (3 papers, 2015 to 2022). "The selectin E gene (SELE) was predicted to be downstream regulated by NFκB via such chemokines (CCL8, CXCL2, CXCL3), while previous studies observed that it activates the PI3K/NFκB pathway in colon cancer." (PMID 27078000, 2016).
cutaneous squamous cell carcinoma (3 papers, 2021 to 2025). "Although photodynamic therapy (PDT) elicited CCL8, which actively brought about an M1 anti-tumor response in cutaneous squamous cell carcinoma, CCL8 is also reported to enhance stemness in cancers." (PMID 38035101, 2023). "Indeed, one study found that CCL8 sensitized mice with cutaneous squamous cell carcinoma to photodynamic therapy by recruiting M1 macrophages." (PMID 34844613, 2021).
dengue (3 papers, 2011 to 2024). "Having higher levels of ALOX-12 and PTAFR expression and lower levels of CCL6/MRP-1, CCL8/MRP-2, CCL12/MCP-5, and IL1R1 expression helps fight dengue." (PMID 38919218, 2024). "The model with CCL8, VPS13C RNA, uPAR protein, and with CCL8, VPS13C RNA and platelets were the best biomarker models for stratifying adult dengue patients at early infection, with sensitivity and specificity up to 83% and 84%, respectively." (PMID 27286230, 2016). "Comparing whole genome expression profiles between patients with acute versus convalescent dengue disease indicated significant abundance of transcripts of the chemokines CCL2 (4,287 fold), CCL8 (160 fold), CXCL10 (30 fold) and CCL3 (17 fold) during acute dengue." (PMID 21810247, 2011).
diabetes (3 papers, 2021 to 2024). "CCL2, CCL8, and CXCL10 have also been demonstrated to play a role in the development of diabetes." (PMID 36299624, 2022). "In people without diabetes SRA1 expression was associated with CCL3 (r = 0.298, p = 0.036), CCL8 (r = 0.344, p = 0.021), CXCL11 (r = 0.400, p = 0.003), TNF-α (r = 0.317, p = 0.030), TGF-β (r = 0.514, p < 0.0001), IL13 (r = 0.310, p = 0.028), and IL18 (r = 0.547, p < 0.0001)." (PMID 34685582, 2021).
esophageal squamous cell carcinoma (3 papers, 2020 to 2023). Esophageal squamous cell carcinoma (ESCC) is a type of esophageal carcinoma (EC) that can affect any part of the esophagus, but is usually located in the upper or middle third. "Previous study revealed that CCL8 can induce epithelial–mesenchymal transition (EMT) in esophageal squamous cell carcinoma cells, thus facilitating tumor cell migration and invasion." (PMID 33146700, 2020). "CCL8 promotes the migration and invasion of esophageal squamous cell carcinoma as well." (PMID 34692697, 2021).
lupus nephritis (3 papers, 2012 to 2025). Glomerulonephritis in the context of systemic lupus erythematosus. "Our data imply that CCL5 and CCL8 might be good targets for improving the therapeutic efficacy of MSCs in ameliorating lupus nephritis." (PMID 37567910, 2023).
pancreatic cancer (3 papers, 2021 to 2022). "However, the role of the CCR5 ligands CCL3, CCL5 and CCL8 in pancreatic cancer remains controversial." (PMID 35954489, 2022). "Our data also suggest that the ligands for the chemokine receptors CXCR3 (CXCL9, CXCL10, CXCL11) and CCR5 (CCL8) might affect the spatial distribution of CD8+ T cells in human pancreatic tumor tissues and enhance the relative T cell trafficking into tumor rich areas." (PMID 35954489, 2022). "CAFs alter the pancreatic cancer microenvironment by the secretion of growth factors such as C-X-C motif chemokine ligand 1 (CXCL1), CXCL12, C-C motif chemokine ligand 8 (CCL8), stromal cell-derived factor-1 (SDF-1), IL-6, IL-11, VEGF and others." (PMID 35883598, 2022).
rheumatoid arthritis (3 papers, 2010 to 2020). A chronic, systemic autoimmune disorder characterized by inflammation in the synovial membranes and articular surfaces. "Recently, increased miR-155 is shown to be associated with increased production of the chemokines CCL3, CCL4, CCL5 and CCL8, and regulate chemokine receptor expression in rheumatoid arthritis patients." (PMID 29162878, 2017). "CCR2 is normally involved in the infiltration of monocytes in inflammatory diseases such as rheumatoid arthritis and its ligands include CCL2, CCL7, and CCL8." (PMID 20976171, 2010).
Sepsis (3 papers, 2017 to 2022). Sepsis is defined as life-threatening organ dysfunction caused by a dysregulated host response to infection. "In addition, increased CCL8 levels have also been shown in septic patients’ plasma compared with healthy volunteers at the early stages of sepsis." (PMID 35285058, 2022). "Several chemokines have been identified as biomarkers for sepsis, such as CXCL8, CXCL13, CCL2, and CCL8." (PMID 32500306, 2020).
AIDS (2 papers, 2023 to 2025). A syndrome resulting from the acquired deficiency of cellular immunity caused by the human immunodeficiency virus (HIV). "CCL8, CXCL13, and IL-1RA levels were elevated in patients with active, but not inactive, SLE versus HC, as well as in patients with SLE versus other AIDs, and the levels of these cytokines correlated with SLE disease activity." (PMID 38098483, 2023). "Specifically, CCL8, CXCL13, and IL-1RA levels were elevated in patients with active, but not inactive, SLE versus HC, as well as in patients with SLE versus other AIDs." (PMID 38098483, 2023). "Additionally, serum levels of CCL8, CXCL13, and IL-1RA were higher in patients with SLE compared with patients with other AIDs, and they correlated with global SLE disease activity." (PMID 38098483, 2023).
delirium (2 papers, 2022 to 2025). A disorder characterized by confusion; inattentiveness; disorientation; illusions; hallucinations; agitation; and in some instances autonomic nervous system overactivity. "LM‐ and AS‐induced delirium led to microglial activation in the hippocampus as evidenced by up‐regulation of microglial activation‐related genes (such as Il6ra, Tyrobp, Cd68, Aif1, Csf1r, and Trem2) and of relevant inflammatory factors (such as Il‐1β, Tnfα, Ccl2, Ccl5, and Ccl8)." (PMID 35713240, 2022).
diffuse large B-cell lymphoma (2 papers, 2022 to 2023). "The results of MR analysis showed that significant causal association between CCL8 [OR (95%CI), 1.360 (1.065–1.734), p = 0.01] and Diffuse large B-cell lymphoma (finn-b-C3_DLBCL)." (PMID 38075694, 2023).
encephalitis (2 papers, 2017 to 2024). An acute inflammatory process affecting the brain parenchyma. "Whether CXCL11 and CCL8 are universal markers of meningitis but not encephalitis, or if HSV-1 and HSV-2 differ in their ability to induce the production of these chemokines, remains to be determined." (PMID 28693588, 2017).
endometrial cancer (2 papers, 2021 to 2022). Primary or metastatic malignant neoplasm involving the endometrium (mucous membrane that lines the endometrial cavity). "Corroborating its pro-tumorigenic character, overexpression of CCL8 in breast and endometrial cancer has been predictive of poor prognoses." (PMID 34884259, 2021).
eosinophilia (2 papers, 2020 to 2022). "CCL8 has been shown to be central to recruiting IL-5 producing Th2 cells, which in turn regulate eosinophilia, thus linking these transcript changes to the hallmarks of DRESS." (PMID 35703984, 2022). "CCL8 induced eosinophilia through recruiting IL-5-producing CCR8+Th2 cell in AD murine model." (PMID 32280674, 2020).
gastric cancer (2 papers, 2020 to 2022). A primary or metastatic malignant neoplasm involving the stomach. "In the intestinal type and diffuse type of gastric cancer, the expression of 28 chemokines with their receptors such as CCL3 and CCL8 and 21 interleukins such as IL7 and IL16 demonstrated significantly statistical difference." (PMID 33426088, 2020).
Granuloma (2 papers, 2010 to 2015). A compact, organized collection of mature mononuclear phagocytes, which may be but is not necessarily accompanied by accessory features such as necrosis. "Up-regulation of CCL6, CCL7 and CCL8 has previously been reported for S. mansoni infection and so might represent a common mechanism whereby macrophages are recruited into schistosome-induced granulomas." (PMID 20161726, 2010).
HCMV infection (2 papers, 2014 to 2021). "We have previously shown that experimental latent HCMV infection of CD34+ progenitor cells alters the cellular secretome resulting in the upregulation of chemokines CCL8, CCL2 and secretion of TGF-β and cellular IL-10 (cIL-10)." (PMID 33912186, 2021). "Taken together, these data suggest that both CCL8 and CXCL10 are produced as a result of the latent HCMV infection of monocytes." (PMID 33912186, 2021).
Hypertension (2 papers, 2023 to 2025). The presence of chronic increased pressure in the systemic arterial system. "Hydralazine also prevented angiotensin II-induced expression of Ccr2, and its ligands Ccl2 and Ccl8, consistent with Ccr2-mediated immune cell infiltration as a key aspect of brain inflammation during hypertension." (PMID 40697973, 2025). "Patients who had improved hypertension 6 months after surgery presented with increased expression levels of the inflammasome activation components (ASC, P2X7, and IL18R), cytokines (CCL8, CXCL2, IKKA, and IL6R), NOD-like receptors (NLRP1), and cell cycle/DNA regulators (TGFb)." (PMID 37867510, 2023).
invasive breast carcinoma (2 papers, 2020 to 2023). A carcinoma that infiltrates the breast parenchyma. "Subsequently, we investigated the correlation between CCL8, TGFBI expression levels and immune infiltrates in invasive breast cancer samples from the TCGA database, respectively." (PMID 37884960, 2023).
ischemia (2 papers, 2022 to 2023). A hypoperfusion of the BLOOD through an organ or tissue caused by a PATHOLOGIC CONSTRICTION or obstruction of its BLOOD VESSELS, or an absence of BLOOD CIRCULATION. "Ccl8 and Ccl7 are kinds of chemokines that attract monocytes to the site of trauma, infection, toxin exposure, and ischemia." (PMID 36139770, 2022).